CLDN6 (claudin 6)
Diseases named in the same sentence as CLDN6 in open-access papers (continued):
Sharing a sentence is not in itself a finding about the gene and the disease.
Nephroblastoma (2 papers, 2025). An embryonal neoplasm characterized by the presence of epithelial, mesenchymal, and blastema components. "CLDN6 expression was also found in nephroblastoma but was rather heterogeneous." (PMID 40149257, 2025). "In tumor samples, the highest expression of CLDN6 was detected in extracranial GCT, the DSRCT sample available in our cohort and nephroblastoma." (PMID 40149257, 2025). "Wilms tumors demonstrated heterogeneous CLDN6 expression, notably absent in the blastemal component." (PMID 40149257, 2025).
teratoma (2 papers, 2021 to 2025). A non-seminomatous germ cell tumor characterized by the presence of various tissues which correspond to the different germinal layers (endoderm, mesoderm, and ectoderm). "In line with mRNA expression data, one mature teratoma sample from a 14-year-old female patient was negative for CLDN6 membrane staining." (PMID 40149257, 2025). "Moreover, prevention of teratoma formation has been also evaluated by immunological treatment, using antibodies against different antigens such as SSEA-5, claudin-6, or using cytotoxic antibodies." (PMID 33585434, 2021). "Within teratoma, only immature but not mature teratoma expressed CLDN6." (PMID 40149257, 2025).
testicular cancer (2 papers, 2023 to 2025). A primary or metastatic malignant neoplasm that affects the testis. "TORL-1-23 is a novel antibody-drug conjugate (ADC) that targets the tumor-associated protein Claudin 6 (CLDN6), which is overexpressed in several types of cancer, including ovarian, endometrial, and testicular cancer." (PMID 40722601, 2025).
uterine cancer (2 papers, 2023 to 2025). Primary or metastatic malignant neoplasm involving the uterine corpus and/or the cervix. "In uterine cancers, CLDN6 was significantly associated with patient age, stage, and survival, reinforcing its role as a context-specific oncogene." (PMID 40687428, 2025).
yolk sac tumor (2 papers, 2023 to 2025). A non-seminomatous malignant germ cell tumor composed of primitive germ cells. "In yolk sac tumors, the expression of CLDN6 appeared to decrease with the patient’s age." (PMID 40149257, 2025).
bladder cancer (1 paper, 2024). "Given that the antitumor effects of Cldn6, Anln, Ccnb1, and Melk have already been verified in bladder cancer, we used these four epitopes in our engineered OMVs." (PMID 38166929, 2024).
cervical adenocarcinoma (1 paper, 2025). An adenocarcinoma arising from the cervical epithelium. "Increased Cldn6 expression in cervical adenocarcinoma cells increases AKR family proteins and resistance to anticancer drugs." (PMID 40361399, 2025).
chronic hepatitis C (1 paper, 2016). "Therefore, it might be feasible to speculate that expression of VLDLR and CLDN6/9 enables HCV to be internalized into various non-hepatic tissues, leading to development of the extrahepatic manifestations that sometimes occur in chronic hepatitis C patients." (PMID 27152966, 2016).
dermatitis (1 paper, 2009). An inflammatory process affecting the skin. "K1 was localized throughout the thickened suprabasal zone of the dermatitis-affected Inv-Cldn6-CΔ196 epidermis, and staining appeared punctate, suggesting a keratin filament bundling defect." (PMID 19915705, 2009). "Second, obvious signs of dermatitis, especially in areas subjected to repetitive mechanical stress during grooming (e.g. the neck and behind the ears), were seen in the aging Inv-Cldn6-CΔ196 epidermis." (PMID 19915705, 2009). "While the distribution of Cldn6, Cldn11, Cldn12 and Cldn18 corresponded to the expanded suprabasal compartment of the dermatitis-affected Inv-Cldn6-CΔ196 epidermis, immunostaining was less intense and membranous localization less evident in lower suprabasal layers." (PMID 19915705, 2009). "However, with aging, Inv-Cldn6-CΔ196 mice suffered dermatitis, often manifested as patent wounds in repetitive grooming areas." (PMID 19915705, 2009).
desmoplastic small round cell tumor (1 paper, 2025). Desmoplastic small round cell tumor (DSRCT) is an aggressive soft tissue cancer that typically arises in serous lined surfaces of the abdominal or pelvic peritoneum, and spreads to the omentum, lymph nodes and hematogenously disseminates especially to the liver. "Our data disclose an age-dependent expression of CLDN6 in normal tissues and an expression of rare but aggressive tumor subtypes, including desmoplastic small round cell tumors (DSRCTs)." (PMID 40149257, 2025).
embryonal carcinoma (1 paper, 2021). A non-seminomatous malignant germ cell tumor characterized by the presence of large germ cells with abundant cytoplasm resembling epithelial cells, geographic necrosis, high mitotic activity, and pseudoglandular and pseudopapillary structures formation. "HNF4α triggered formation of the functional TJPs occludin and claudin-6/7 and the establishment of polarized epithelial morphology in F9 embryonal carcinoma cells." (PMID 34819492, 2021).
endometrial adenocarcinoma (1 paper, 2022). "Knockdown of CLDN6 significantly inhibited cell proliferation and the colony numbers of human endometrial adenocarcinoma cells via remarkable reduction of p-AKT, p-PI3K, and mTOR expression levels." (PMID 36362009, 2022).
endometrial tumors (1 paper, 2025). "For example, a CLDN6-targeted antibody–drug conjugate (ADC) has shown preclinical efficacy in CLDN6+ ovarian and endometrial tumors." (PMID 40687428, 2025). "Moreover, CLDN9 expression strongly correlated with CLDN6 expression in endometrial tumors." (PMID 40687428, 2025).
endotoxemia (1 paper, 2022). "Our previous study confirmed that Fn041 directly regulates the mRNA expression of several tight junction genes, such as Zo1, occludin, and claudin-6, to prevent barrier damage and endotoxemia caused by a high-fat diet." (PMID 35369106, 2022).
germinoma (1 paper, 2025). A malignant germ cell tumor arising in the central nervous system. "Other intracranial tumor entities that may express CLDN6 are germinoma and primitive neuroectodermal tumor." (PMID 40149257, 2025).
metastatic tumors (1 paper, 2013). "Our data show that the expression of claudin-6 in 36 ovarian papillary serous carcinomas is significantly higher than in 26 ovarian serous adenomas; claudin-6 expression in metastatic tumors was significantly higher than in the tumors without metastasis." (PMID 24245968, 2013).
myeloid leukemia (1 paper, 2023). A clonal proliferation of myeloid cells and their precursors in the bone marrow, peripheral blood, and spleen. "Beyond GCT, CLDN6 would be also a suitable target for other CLDN6+ tumor entities, such as myeloid leukemia, ovarian, endometrial, or urothelial carcinoma." (PMID 36991316, 2023).
pediatric tumor (1 paper, 2025). "This is particularly important because the highly aggressive intracranial pediatric tumor AT/RT expresses CLDN6 and this entity occurs most commonly in infants and toddlers." (PMID 40149257, 2025).
serous ovarian carcinoma (1 paper, 2026). "Despite this potential, the clinical significance of CLDN6 expression in advanced-stage high-grade serous ovarian carcinoma (HGSC)-specifically its role in platinum resistance-remains poorly understood." (PMID 42072801, 2026).
squamous cell carcinoma (1 paper, 2024). A carcinoma arising from squamous epithelial cells. "Claudin-6 was significantly more frequent and most abundantly positive in adenocarcinoma (AC) than in squamous cell carcinoma (SCC), and was associated with poor prognosis in 164 patients with NSCLC from the University Hospital of Kuopio." (PMID 38841188, 2024).
Stroke (1 paper, 2024). Sudden impairment of blood flow to a part of the brain due to occlusion or rupture of an artery to the brain. "Entering the IgA responses to the separate epitopes (regression #6) showed that 28.4% of the variance in the IRS/CIRS ratio is explained by IgA claudin-6, previous stroke, and age (all positively associated)." (PMID 38379706, 2024).
tumor (87 papers, 2012 to 2026). "Our results supported the view that CLDN6 was associated with ferroptosis in xenograft tumor models." (PMID 39984471, 2025). "High expression of CLDN6 was associated with tumor differentiation of hHCC according to the Cancer Genome Atlas (TCGA) database." (PMID 38731853, 2024). "In GAC, first studies with smaller cohorts demonstrated that the expression of CLDN6 is associated with tumor cell proliferation and increased invasiveness; additionally, a correlation between CLDN6 expression and reduced overall survival was observed." (PMID 37592303, 2023). "The endocytosis-related proteins PAR3 and Claudin-6, which control cell polarity, are closely associated with tumour polarity, permeability, and adhesion." (PMID 35517414, 2022). "Functional tests showed that CLDN6 is not only a tumor associated antigen, but also has a strong carcinogenic effect in LIHC." (PMID 36482887, 2022). "For proof-of-concept studies, we engineered the TCAR to target two well-characterized and safe tumor-associated antigens from the Claudin family of tight junction proteins, Claudin 6 (CLDN6) and Claudin 18.2 (CLDN18.2)." (PMID 36923303, 2022). "As a member of CLDNs, CLDN6 is also associated with tumor initiation and progression in a range of cancers." (PMID 34948213, 2021). "On the contrary, levels of Cldn1,Cldn4,Cldn6,Cldn9,Cgn,F11r, and Cdh1, associated with exacerbated inflammation, perturbation of the TJ assembly, and even with mesenchymal transformation or tumour progression, were overexpressed." (PMID 37794493, 2023). "Similarly, VLPs harboring CLDN6, a tumor-associated antigen, were used to identify a panel of anti-CLDN6 mouse and chicken antibodies with high affinity and specificity." (PMID 38135942, 2023). "Overall, the results suggest that claudin-6 expression, a protein mainly expressed in fetal tissues dedifferentiated cells and strongly linked to the development of cancer, co-associates with genes involved in tumor-suppressing mechanisms." (PMID 36430456, 2022). "Therefore, our results strongly suggest that overexpression of claudin-6 is strongly associated with enhanced tumor aggressiveness and invasiveness promotion." (PMID 36430456, 2022). "Immunohistochemical staining of clinical samples showed that CLDN6 was lowly expressed in lymphatic metastasis tissues, suggesting that CLDN6 loss may promote tumour metastasis." (PMID 32093760, 2020). "CLDN6 loss in tumour tissues correlates with tumour metastasis and poor prognosis." (PMID 32093760, 2020). "Moreover, loss of CLDN6 expression under therapy pressure has been described in preclinical studies, and future work will be required to understand and modulate CLDN6 expression in different tumor types." (PMID 40149257, 2025). "Furthermore, univariate analysis revealed that tumor diameter, tumor embolus, nerve invasion, T stage, N stage, lymph node involvement, and high CLDN6 expression were risk factors in GC, and multivariate analysis showed that tumor embolus and T stage were the major risk factors." (PMID 31827075, 2019). "Leveraging these biological characteristics of CLDN6, we discovered that significant tumor regression was observed in mice treated with SAIL66 following carboplatin pretreatment." (PMID 41628300, 2026). "CLDN6 expression was evaluated via immunohistochemistry (IHC) on formalin-fixed paraffin-embedded (FFPE) tumor samples." (PMID 42072801, 2026). "In one study, CLDN6 was expressed at low levels in a CRC cell line (SW1116); when CLDN6 was experimentally overexpressed, it suppressed the cells’ migratory and invasive abilities, apparently by activating the tumor-suppressive TYK2/STAT3 pathway." (PMID 40687428, 2025). "Therapeutics targeting CLDN6 have demonstrated initial clinical efficacy given its low expression in healthy tissues and tumor-restricted expression." (PMID 40808959, 2025). "Our analysis of RNA-seq data suggested that CLDN6 is an interesting target for several pediatric tumor entities." (PMID 40149257, 2025).
tumor (continued). "Due to the limited number of samples in our cohort, we were unable to analyze the correlation between CLDN6 expression and tumor stage or histological subtypes." (PMID 40149257, 2025). "The novel radiotracers [89Zr]Zr-DFO-IMAB027 and [177Lu]Lu-DOTA-IMAB027 achieved the noninvasive assessment of CLDN6 expression and inhibited tumor growth in EC with high CLDN6 expression, respectively." (PMID 39915118, 2025). "Currently, anti-CLDN6 monoclonal antibodies have been used to synthesize antibody–drug conjugates, which have demonstrated robust tumor regression in ovarian and endometrial cancers." (PMID 39915118, 2025). "XmAb541, designed to engage CD3 on T-cells and CLDN6 on tumor cells, is being evaluated in gynecologic malignancies such as ovarian and uterine cancers (NCT06276491)." (PMID 41211166, 2025). "Eight genes exhibited greater than 340-fold increases in expression in tumor tissues (CLDN6, KLK7, WNT10A, MYBL2, MAL2, KRT7, PRSS8, EPCAM; Median (Range) of fold increase = 344 (261–7267))." (PMID 41465326, 2025). "Here, we assessed the expression of CLDN6 in normal tissues and tumor samples from children on the RNA and protein levels." (PMID 40149257, 2025). "Preclinical studies demonstrated that several CSC-specific antigens (e.g., GD2, HER2, CD133, PSCA, CLDN6)-targeted CAR-NK cells displayed superior anti-tumor activity 131-136." (PMID 39990669, 2025). "Mechanistic studies have shown that CLDN6 promotes tumor progression via the CLDN6/tight junction protein 2 (TJP2)/yes-associated protein 1 (YAP1) axis, activating the Hippo signaling pathway." (PMID 41425250, 2025). "A recent study on CLDN6-targeted CAR-NK cells found that combining them with anti-PD-L1 antibodies synergistically boosted anti-tumor efficacy, highlighting the potential of pairing CAR-NK cells with PD-1/PD-L1 inhibitors for cancer therapy." (PMID 41425568, 2025). "To identify tumor entities with high expression of CLDN6, we used RNA-sequencing (RNA-seq) data available via the St." (PMID 40149257, 2025). "An alternative is targeting constitutively expressed tumor-maintenance antigens, such as B7-H3 or Claudin 6, which are less prone to downregulation." (PMID 41262250, 2025). "Recombinant IgG1 control antibodies and concentrated supernatants from engineered B cell culture were tested against the CLDN6-expressing tumor cell line PA-1, which express CLDN6 at high levels." (PMID 40808959, 2025). "Label uptake was detected only in the combination of B cells engineered to express CLDN6-specific BCRs and tumor cell lines expressing CLDN6." (PMID 40808959, 2025). "Given its differential expression between tumor and normal tissues, CLDN6 is considered a promising therapeutic target for TRT." (PMID 39915118, 2025). "The expression of CLDN6 in the category “other tumor entities” was <104, with the exception of the mentioned DSRCT sample." (PMID 40149257, 2025). "The radiotracer [89Zr]Zr-DFO-IMAB027 showed high contrast when visualizing CLDN6-expressing xenografts for PET imaging, and [177Lu]Lu-DOTA-IMAB027 induced rapid tumor regression in both the TE-1-CLDN6 and the CLDN6-PDX models." (PMID 39915118, 2025). "In samples from high-risk patients (n = 3), one sample isolated from a lymphnode metastasis showed a high CLDN6 expression, but in only 5% of the tumor cells." (PMID 40149257, 2025). "In an in vitro study, silencing the CLDN6 gene resulted in decreased tumor proliferation, migration, and invasion with upregulated E-cadherin and downregulated N-cadherin and vimentin." (PMID 38731853, 2024). "Their representative genes include the tumor suppressor genes LHPP, VGLL4, USP53, and CLDN6, which have been reported to play significant anti-tumor functions in a variety of cancer types." (PMID 38831454, 2024). "CLDN6 has been investigated as a potential cancer therapy due to its specific enrichment in tumor tissue." (PMID 38371623, 2024).
tumor (continued). "Efficacy has been disappointing on the whole, although there are pointers towards greater efficacy when more tumour-selective targets are selected (e.g., claudin 18.2, claudin 6)." (PMID 36829563, 2023). "Administration of CD3 × CLDN6 RiboMAB to an ovarian cancer xenograft mouse model resulted in complete tumor elimination compared to the control and antibody protein treatment groups." (PMID 37550567, 2023). "GCT and EOC patients had the strongest CLDN6 expression, with an average of >80% tumor cells with 2+/3+ (intermediate/strong) staining intensity." (PMID 37872225, 2023). "The BNT211 is another immunotherapy candidate produced by BioNTech and can act by targeting the tumor-specific antigen Claudin-6 (CLDN6)." (PMID 37514158, 2023). "IHC of lung metastatic tumor tissues of mice showed the expression intensity of CLDN6 was consistent with WIP and LC3." (PMID 36935496, 2023). "Two achieved SD as BOR, two were treated without prior LD and experienced PD, as did the fifth patient, who entered the study with a rapidly progressing tumor (86% increase in target sum from screening to ACT) having only 50% 2+/3+ CLDN6-positive tumor cells." (PMID 37872225, 2023). "For the 40 tumors above the best cut-off for CLDN6 expression, 35 belonged to the CIN subgroup (87.5%), four to the genome stable subgroup (10%), and one tumor belonged to the EBV-associated group (2.5%)." (PMID 37592303, 2023). "CAR-T approach targeting the extracellular domain of another claudin (CLDN6) has been shown to successfully mediate a complete regression of CLDN6-expressing human tumor cells xenografted in immunodeficient mice." (PMID 34131154, 2021). "The positive expression of CLDN6 in hHCC tissues was related to the degree of tumor differentiation." (PMID 34405008, 2021). "In order to further evaluate the effect of CLDN6 on in vivo tumorigenesis, we established xenograft implantation tumor models." (PMID 35008557, 2021). "The relationship between CLDN6 and tumor cell proliferation and apoptosis is confirmed by gain- and loss-of-function experiments in a variety of tumor cells." (PMID 34948213, 2021). "As a result, hHCC tissues highly expressed CLDN6, and the expression was related to the degree of tumor's differentiation." (PMID 34405008, 2021). "Many studies have shown that CLDN6 affects tumor cell migration and invasion, but there is a paradox in that CLDN6 both inhibits and promotes migration and invasion." (PMID 34948213, 2021). "Here, a new finding is that CLDN6 was upregulated under hypoxia, a commonly recognized factor that promotes tumor metastasis." (PMID 32093760, 2020). "The roles of the CLDN6/SENP1/HIF-1α signaling on tumor metastasis were evaluated by function experiments and clinical samples." (PMID 32093760, 2020). "Our data strongly supports the role of CLDN6 in mediating hypoxia-induced tumour metastasis, at least partially by mediating HIF-1α." (PMID 32093760, 2020). "We found that overexpression of YAP1 partially reversed the tumor-inhibiting effect CLDN6 knockdown." (PMID 31827075, 2019). "Subcutaneous tumor model showed that suppression of CLDN6 expression reduced tumor load, while overexpression of YAP1 reversed this trend of tumor load reduction." (PMID 31827075, 2019). "In summary, the MV-derived tumor-vaccines were able to induce immunity against the endogenous TAA CLDN6." (PMID 29203786, 2017). "Of note, 3 out of 7 mice of the MVvac2-gag-CLDN6 group were free of any metastatic nodules in the lung, while in the other groups robust tumor growth was evident in all animals (in total n = 23)." (PMID 29203786, 2017). "To investigate the potential synergism in anti-tumoral efficacy of oncolytic and vaccine properties, we chose Ovalbumin and an ideal tumor antigen, claudin-6, for pre-clinical proof of concept." (PMID 29203786, 2017).